INS (insulin)
Diseases named in the same sentence as INS in open-access papers (continued):
Sharing a sentence is not in itself a finding about the gene and the disease.
Insulin resistance (continued). "Insulin resistance is defined as a reduction in tissue response to insulin stimulation hence insulin resistance (IR) is characterized by defects in uptake and oxidation of glucose, a decrease in glycogen synthesis, and, to a smaller degree, the ability to suppress lipid oxidation." (PMID 40005397, 2025). "IDE may participate in the degradation of insulin within endosomes, contributing to the regulation of insulin availability and preventing prolonged insulin action that could promote insulin resistance and impair glucose metabolism." (PMID 40724942, 2025). "However, the observation that cells treated with dexamethasone alone exhibited statistically lower insulin signaling and reduced mitochondrial function provides additional evidence linking the development of insulin resistance with mitochondrial dysfunction." (PMID 40422898, 2025). "Clinical findings in recent decades have provided detailed information for reference in model formulations including high insulin-induced insulin resistance, reduced insulin clearance, the coexistence of positive and negative effects of FFAs on beta-cell function, and so on." (PMID 40568093, 2025). "TNF-α inhibits insulin signaling and insulin-regulated glucose uptake, thus suggesting that the insulin resistance of pregnancy may be mediated through this cytokine." (PMID 39035597, 2024). "Excessive lipid availability induces insulin resistance in the liver, which manifests as the inability of insulin to suppress hepatic gluconeogenesis and glucose release in the circulation, thus contributing to fasting hyperglycemia and eventually type 2 diabetes." (PMID 37934800, 2024). "Moreover, TNF-α compounds insulin resistance by suppressing key genes involved in adipocyte development and insulin signaling." (PMID 38826152, 2024). "Analysis of adipocyte protein responses to insulin in this more readily accessible abdominal subcutaneous fat could help dissect the mechanisms of systemic insulin resistance in UBO for both male and female participants." (PMID 38602778, 2024). "The increased mRNA expression of SREBF1 induced by insulin supplementation in obese cows, is a critical factor for significantly upregulating lipogenic genes, and also a key target for improving insulin resistance and the significant reduction in NEFA in obese cows." (PMID 39881718, 2024). "Additionally, AO and VGX influenced the whole-body metabolism, leading to an increase in the body weight and visceral fat, a decrease in the skeletal muscle mass, and an elevation in the serum insulin concentration and insulin resistance." (PMID 39063072, 2024). "And rs2025066 had a significant correlation with both insulin resistance and fasting insulin." (PMID 38568153, 2024). "Mitochondrial diabetes development is primarily due to β-cell deficiencies and unlike T2D, it less often involves insulin resistance and is frequently treated with insulin supplementation." (PMID 38404962, 2024). "In T2DM, the response to insulin is impaired, which is referred to as insulin resistance." (PMID 39519429, 2024). "Furthermore, alterations in lipid metabolism in WAT induce elevated levels of triglycerides and FFAs in plasma that accumulate in insulin-sensitive tissues and contribute to insulin resistance in skeletal muscle." (PMID 39458933, 2024). "However, numerous factors associated with the obese state have the capacity to induce insulin resistance in differentiated 3T3-L1 adipocytes including TNF-α, IL-6, dexamethasone, high insulin, glucosamine, and exposure to hypoxic environment." (PMID 39415617, 2024). "Insulin resistance describes how sensitive cells are to the effects of insulin." (PMID 40604159, 2024). "In postmenopausal women with T2D, estrogen therapy reduced fasting glucose and insulin as well as HbA1c (a marker of chronic hyperglycemia), and decreased the homeostatic model assessment for insulin resistance (HOMA-IR) index to a greater extent than in postmenopausal women without diabetes." (PMID 39225098, 2024).
Insulin resistance (continued). "High levels of fructose increase hepatic insulin resistance and may result in increased insulin levels." (PMID 39141644, 2024). "In a cohort of 5- to 9-year-old prepubertal children with overweight and obesity, we observed early insulin resistance driven by high insulin levels, as fasting glucose levels remained normal, and elevated markers of inflammation including CRP and the leptin/adiponectin ratio." (PMID 38680993, 2024). "Potentially, increased DPP-4 activity in GDM and EGWG may influence the development of inflammation, impair insulin signaling, and, finally, contribute to insulin resistance." (PMID 38339106, 2024). "Additionally, the PCOS group display higher insulin levels, indicative of possible insulin resistance." (PMID 38600539, 2024). "It has been suggested that the liver is more prone to developing insulin resistance compared to muscle or adipose tissue and that the insulin resistance of muscle and adipose tissue may result from hepatic insulin resistance." (PMID 38989003, 2024). "T2D risk alleles at index SNVs showed a gradient of effects on insulin-related endophenotypes across clusters, representing a cline from insulin production and processing in the two beta-cell-dysfunction clusters through to insulin resistance that was most extreme in the lipodystrophy cluster." (PMID 38374256, 2024). "Consequently, obesity is caused by a persistent imbalance between energy expenditure and intake, which results in aberrant fat storage in adipose tissues, improper lipid metabolism, and excessive insulin production, which induces insulin resistance." (PMID 38276548, 2024). "Furthermore, SIT treatment produced a clear improvement in insulin signaling, as was indicated by decreased markers for insulin resistance and increased markers for insulin sensitivity." (PMID 39074126, 2024). "Moreover, BCA treatment actually controls hyperglycemia in T2DM rats with regard to the reduction in insulin resistance and increased insulin sensitivity at the cellular level." (PMID 38683825, 2024). "Furthermore, the increased demand for insulin secretion due to insulin resistance in the elderly places an additional burden on the β cells, further exacerbating their dysfunction." (PMID 38794702, 2024). "TNF-α activates T lymphocytes and macrophages, inducing the production of other cytokines and cell adhesion molecules and potentially inducing insulin resistance by reducing insulin signaling and promoting the serine phosphorylation of insulin receptor substrate 1 (IRS1)." (PMID 39408723, 2024). "SGLT1 inhibition could increase insulin secretion to alleviate insulin resistance by several intracellular mechanisms." (PMID 39474649, 2024). "Furthermore, homeostatic model assessment for insulin resistance (HOMA‐IR) as well as fasting insulin levels and serum fast blood glucose were reduced, too." (PMID 39139973, 2024). "Blocking TLR4 can improve the insulin-dependent intake of glucose and alleviate insulin resistance induced by HFD in mice, which may be because the knockout of TLR4 leads to a decrease in inflammatory factors." (PMID 38275739, 2024). "By incorporating aerobic exercise recommendations and personalized guidance, multidimensional exercise management interventions address the increased demand for insulin during pregnancy and help mitigate the adverse effects of insulin resistance on blood glucose levels." (PMID 39219840, 2024). "Moreover, the neuroprotective effect of anti-diabetic medications in patients with PD confirms the importance of insulin signaling and insulin resistance in PD." (PMID 39830652, 2024). "Brain insulin resistance is defined as the reduced physiological actions of insulin in the brain." (PMID 39518747, 2024).
Insulin resistance (continued). "Another population-based study with multivariable linear regression models was built to assess the associations of ferritin and transferrin saturation with blood levels of glucagon-like peptide-1, insulin, homeostatic model assessment-insulin resistance, fasting plasma glucose, and hemoglobin." (PMID 39685901, 2024). "The chronic and untreated life-threatening disease is due to either pancreatic lesions resulting in impaired insulin secretion or peripheral cells becoming unresponsive to insulin to a variable degree and its subsequent metabolic effects (so-called peripheral insulin resistance)." (PMID 38572446, 2024). "RS may improve insulin resistance, lower fasting blood glucose and insulin levels, and attenuate oxidative stress in patients with T2DM." (PMID 38903985, 2024). "AT administration for 12 weeks reduced body weight and organ weights, including liver, pancreas, and white and brown adipose tissue, and improved plasma profiles such as glucose, insulin, homeostasis model assessment of insulin resistance, triglyceride (TG), and total cholesterol in HFD-fed mice." (PMID 38612554, 2024). "Obesity is correlated with insulin resistance, elevated insulin, and glucose levels." (PMID 38790245, 2024). "Trehalose has received much attention for its ability to regulate glucose homeostasis, increase insulin sensitivity, and reduce insulin resistance, and may serve as a therapeutic agent for diabetes." (PMID 38195648, 2024). "Endoplasmic reticulum stress results in increased production of proinflammatory cytokines, such as TNF-α and interleukin 6, which further exacerbate inflammation, increase cortisol levels, and promote insulin resistance via the disruption of the insulin signaling pathway." (PMID 39339762, 2024). "Indeed, any factors that reduce IRS-1 phosphorylation or induce serine IRS-1 phosphorylation at the 307 site by some kinases, such as IKKβ/NF-κB and c-Jun N-terminal kinase (JNK), would impair insulin signal transduction and lead to insulin resistance." (PMID 38952394, 2024). "Some isoforms of the PLA2, Dis, and Ctm-like myotoxin families have been described to show modulatory effect in insulin resistance models, as Glib, these peptides can sensitize the β-pancreatic cells to insulin." (PMID 39398348, 2024). "Moreover, studies have demonstrated that Corydalis can promote insulin release, reduce insulin resistance, and regulate the gut microbiota, thereby improving diabetic complications." (PMID 39687865, 2024). "As insulin resistance progresses within adipose tissue, excess lipolysis occurs, which leads to increased production of free fatty acids and ectopic accumulation of fat within the organs that are sensitive to insulin." (PMID 39906040, 2024). "The scale of My Opinion on Insulin for psychological insulin resistance in all dimensions." (PMID 39036047, 2024). "Similar observations have been reported in non-critically ill patients with type II diabetes mellitus, in whom the level of HOMA-insulin resistance index (HOMA-IR) in the insulin-glargine group was significantly lower than that observed in the standard-care group." (PMID 38365663, 2024). "However, as we explored in section 5.1, NOD1 regulation of the IRS1/Akt pathway hinders insulin signaling, inducing insulin resistance." (PMID 39906040, 2024). "Moreover, SIT treatment resulted in a notable improvement in insulin signaling, as evidenced by decrease in the markers for insulin resistance and increase in insulin sensitivity signaling pathway in the ischemic myocardium." (PMID 39074126, 2024). "Insulin’s diminished impact on its target tissues is known as insulin resistance." (PMID 38534454, 2024). "After 10 weeks of training, there were significant trends of decreasing fasting glucose (P < .05), insulin (P < .05), insulin resistance indices (P < .05), HbA1c (P < .01), and triglyceride (P = .064), while total cholesterol (P < .05) significantly increased in the E group." (PMID 39029066, 2024).
Insulin resistance (continued). "In contrast, T2DM is characterized by insulin resistance, where the body’s cells do not respond effectively to insulin, coupled with a relative insulin deficiency." (PMID 38444587, 2024). "Also, silymarin improves insulin sensitivity and reduces insulin resistance, as indicated by lower HOMA-IR scores." (PMID 39407506, 2024). "Furthermore, insulin-sensitizing adipokine increases metabolic diseases to compensate for insulin resistance and inflammatory complications, contributing to the development of MAFLD." (PMID 38612504, 2024). "Over time, insulin resistance can lead to increased insulin production as the body attempts to overcome this resistance, which may strain the pancreas and eventually contribute to the development of T2DM." (PMID 39335472, 2024). "Notably, fibrates significantly reduce fasting serum glucose levels, insulin levels, and insulin resistance." (PMID 39057711, 2024). "It impairs insulin signaling and contributes to the development of insulin resistance." (PMID 39683486, 2024). "Furthermore, ASs like sucralose and aspartame can disrupt insulin signaling, inducing hyperinsulinemia and insulin resistance by altering glucose transporter expression and insulin receptor sensitivity." (PMID 39449954, 2024). "Recent studies have linked BPA exposure to insulin resistance and glucose intolerance, and BPA significantly decreased the protein levels of insulin signaling molecules such as IR, IRS, AKT, AS160, and GLUT4, thus decreasing glucose uptake and oxidation in the muscle." (PMID 38200540, 2024). "Nanozymes have shown promise in improving insulin sensitivity and reducing insulin resistance." (PMID 38711066, 2024). "Specifically, improved insulin sensitivity related to physical activity may be important, as accumulating evidence suggests that impaired glucose tolerance and insulin resistance play a role in pancreatic carcinogenesis." (PMID 39518035, 2024). "Consequently, it initiates the process of insulin resistance through suppression of intracellular insulin signaling, exaggerates oxidative stress, and inflammation, and decreases blood supply to the skeletal muscle and pancreas." (PMID 38671256, 2024). "Insulin resistance results in increased concentrations of circulating insulin, which is hypothesized to have tumor-promoting effects in the pancreas, although the exact underlying mechanisms remain unknown." (PMID 39518035, 2024). "In parallel, insulin resistance, that was evident in HFD-fed wild type mice relative to SCD-fed controls, was less pronounced in HFD-fed Alx3-deficient mice, which were more sensitive to insulin than controls." (PMID 39129011, 2024). "CPZ-induced insulin resistance appeared to be associated with increased plasma glucose levels rather than insulin levels, in contrast to the insulin resistance induced by MIF." (PMID 38802393, 2024). "However, insulin-mediated vasodilation is impaired in individuals with insulin resistance, leading to reduced glucose uptake in peripheral tissues." (PMID 39759452, 2024). "While genetic biomarkers have been identified, indicating the multifaceted nature of GDM involving hormonal changes, insulin resistance, and impaired insulin secretion, there remains a dearth of exploration into the enduring health implications for both mothers and their children." (PMID 39355538, 2024). "However, later studies have established that the brain is regulated by insulin and demonstrated the occurrence of insulin resistance in the brain." (PMID 38818523, 2024). "In addition, BAs can ameliorate the T2DM symptoms by relieving inflammatory response, promoting insulin secretion, relieving endoplasmic reticulum stress, and inhibiting insulin resistance." (PMID 38835663, 2024). "Moreover, in-vitro and in-vivo studies have shown that LF improves insulin sensitivity even in the presence of existing insulin resistance, reduces weight gain, and regulates blood sugar levels, leptin, and lipid levels in animal models." (PMID 39092264, 2024).
Insulin resistance (continued). "Insulin resistance occurs when insulin-sensitive tissues (e.g., liver, adipose tissue, and skeletal muscle) become progressively less responsive to insulin, resulting in reduced glucose uptake and suppression of endogenous (primarily hepatic) glucose production." (PMID 39420751, 2024). "However, Nppa−/− mice fed HFD exhibited clear signs of whole-body insulin resistance reflected by elevated plasma insulin levels during the glucose tolerance test (GTT) and reduced insulin sensitivity." (PMID 39383215, 2024). "Therefore, it is essential to explore how β2-chimaerin influences insulin signaling in states of insulin resistance." (PMID 39598690, 2024). "Insulin resistance and impaired insulin secretion are major hallmarks of type 2 diabetes." (PMID 39013950, 2024). "Our finding of worsened insulin sensitivity only in males is likely related to hormonal differences between the sexes, as estrogen, a predominately female hormone, has protective effects against insulin resistance." (PMID 38631892, 2024). "Furthermore, impaired triglyceride clearance across adipose tissue is observed in obesity, insulin resistance, and type 2 diabetes (T2D) due to reduced insulin-mediated stimulation of LPL activity." (PMID 38755663, 2024). "Insulin resistance occurs when there is a reduced response to insulin signaling." (PMID 38999025, 2024). "Insulin resistance (IR), which is characterized by the inability of cells to respond to the action of insulin, is a prominent feature of T2DM and is significantly associated with various diseases, including cardiovascular disease, CKD, and cognitive impairment." (PMID 39466812, 2024). "They illustrated that higher adherence to a nutrient pattern, rich in vitamins A, C, B6, potassium, and fructose had favorable effects on insulin, homeostasis model assessment-Insulin resistance (HOMA-IR), and Homeostatic Model Assessment of insulin Sensitivity (HOMA-S), during 3 years of follow-up." (PMID 38310135, 2024). "Under conditions of chronic low-grade inflammation in obesity and type 2 diabetes induced by microbial dysbiosis, diaminopimelic acid activates nucleotide-binding oligomerization domain-containing protein 1 which stimulates insulin resistance and insulin trafficking in β cells." (PMID 39394552, 2024). "TMAO has been found to affect insulin signal transduction and promote insulin resistance." (PMID 39200098, 2024). "Despite the similarities in caloric intake and body weight between the two groups, the rats fed SPs on a 3-h time-restricted feeding schedule for 14 weeks showed glucose intolerance, insulin resistance with disruption of hepatic insulin signaling, and hyperplasia of pancreatic β-cells." (PMID 38561446, 2024). "HOMAIR focuses on the relationship between fasting hepatic glucose production and β-cell insulin secretion to describe baseline insulin resistance, while the Matsuda index of insulin sensitivity describes the whole-body response to a glucose load throughout an oral glucose tolerance test." (PMID 39344511, 2024). "These factors disrupt insulin signaling pathways and contribute to the onset of insulin resistance." (PMID 38449844, 2024). "This could potentially suppress islet cell functionality from afar, away from the PanIN lesions or cancerous sites, and/or interfere with insulin signaling pathways, culminating in insulin resistance." (PMID 39596226, 2024). "Adipose tissue inflammation may induce systemic insulin resistance via the circulating cytokines (e.g., TNFα and IL-6) secreted by M1 macrophages that attenuate insulin signaling in the liver and the skeletal muscle." (PMID 38256005, 2024). "We hypothesize that as little as 1 minute of comfortable pace SCD induces significant improvements in glucose, insulin, and insulin resistance and that SCD effects are amplified in a dose-response manner." (PMID 38572086, 2024).